SNORD114-17 (small nucleolar RNA, C/D box 114-17)
Synonyms: 14q(II-17)
Gene: Small nucleolar RNA gene on chromosome 14 (100,974,806 to 100,974,880, forward strand). Ensembl gene ENSG00000201569.
Gene Ontology:
Biological process: RNA processing
Cellular component: nucleolus
Homologues: Orthologues: chimpanzee SNORD114-17 (100% identical), macaque SNORD114-17 (97% identical). Paralogues in human: SNORD114-3 (89% identical), SNORD114-12 (83% identical), SNORD114-14 (81% identical), SNORD114-13 (79% identical), SNORD114-4 (79% identical), SNORD114-11 (77% identical), SNORD114-19 (77% identical), SNORD114-23 (77% identical), SNORD114-21 (76% identical), SNORD114-1 (75% identical), SNORD114-15 (75% identical), SNORD114-16 (73% identical), and 26 more.
Diseases named in the same sentence as SNORD114-17 in open-access papers:
SNORD114-17 is named in the same sentence as 1 disease in open-access papers, as found by Europe PMC text mining. Sharing a sentence is not in itself a finding about the gene and the disease. The quoted sentences say what the papers report.
cancer (1 paper, 2020). A tumor composed of atypical neoplastic, often pleomorphic cells that invade other tissues. "In addition, SNORD114‐17 is involved in several well‐known cancer‐related pathways, such as PI3K‐AKT signaling and the ECM receptor, suggesting that SNORD114‐17 may be an important regulator of the malignant phenotype." (PMID 31943178, 2020).